PTH (parathyroid hormone)
Diseases named in the same sentence as PTH in open-access papers (continued):
Sharing a sentence is not in itself a finding about the gene and the disease.
secondary hyperparathyroidism (continued). "However, a persisting elevated intact parathyroid hormone serum level may be observed, demonstrating that reduced parathyroid hyperplastic tissue may still be associated with severe secondary hyperparathyroidism." (PMID 23232027, 2012). "Therefore low serum phosphate levels may have been a cause for decreased stimulus for PTH secretion and hence the lesser number of respondents with secondary hyperparathyroidism." (PMID 22457762, 2012). "Her persistently raised PTH with normal calcium and vitamin D likely reflects either secondary hyperparathyroidism (compensatory/early), physiological fluctuation, or normocalcemic primary hyperparathyroidism." (PMID 41589093, 2026). "The review of all 14 reported cases confirms a consistent phenotype of neonatal secondary hyperparathyroidism with universal parathyroid hormone (PTH) elevation, frequent fractures and respiratory distress." (PMID 41951207, 2026). "PTH-calcium studies from India indicated that 25(OH)D levels >12 ng/mL are sufficient to maintain normocalcemia and suppress secondary hyperparathyroidism, thereby questioning the validity of global thresholds." (PMID 41502833, 2026). "Hyperparathyroidism, that is, excess production of PTH, is caused by a parathyroid tumor (primary hyperparathyroidism, PHPT), chronic kidney disease (CKD), or vitamin D deficiency (secondary hyperparathyroidism)." (PMID 40164571, 2025). "Tertiary hyperparathyroidism (THPT) arises in patients with chronic kidney disease (CKD) as a consequence of prolonged secondary hyperparathyroidism and is marked by autonomous parathyroid hormone (PTH) secretion." (PMID 41301699, 2025). "In rats with renal failure, a high phosphorus diet has been shown to induce changes in bone microstructure, affecting both the cortical and trabecular bone compartments, accompanied by increased serum PTH and secondary hyperparathyroidism." (PMID 40573160, 2025). "Epfn is therefore a promising therapeutic target for the regulation of PTH production in patients with primary and secondary hyperparathyroidism." (PMID 40164571, 2025). "Then, it would be especially interesting to find out if individuals with advanced secondary hyperparathyroidism still had an inverse correlation between serum Mg and PTH." (PMID 39791168, 2025). "In children with end-stage kidney disease (ESKD), a decrease in mean serum intact parathyroid hormone (iPTH) levels was observed following 6 months of cinacalcet treatment for secondary hyperparathyroidism (SHPT)." (PMID 40837352, 2025). "MA is a factor leading to a decrease in the level of 1,25-dihydroxyvitamin D3 (calcitriol) in serum and an increase in parathyroid hormone (secondary hyperparathyroidism) and FGF23." (PMID 40870903, 2025). "Inflammatory cytokines can also modulate PTH gene expression and secretion, potentially accelerating the onset of secondary hyperparathyroidism." (PMID 41301699, 2025). "This condition triggers secondary hyperparathyroidism, characterized by elevated parathyroid hormone (PTH) levels, which in turn stimulate osteoclastic bone resorption to maintain serum calcium concentrations." (PMID 40831018, 2025). "The major biochemical difference between these two types of hyperparathyroidism is the low serum calcium levels in secondary hyperparathyroidism versus the high calcium levels in primary hyperparathyroidism, with both having elevated PTH levels." (PMID 41210046, 2025). "Third, increased secondary hyperparathyroidism prevalence is correlated with obesity with characteristic of high parathyroid hormone level, thereby leading to low BMD." (PMID 40455716, 2025). "Dysregulated PTH secretion can lead to conditions such as primary or secondary hyperparathyroidism, often accompanied by renal diseases." (PMID 41048434, 2025). "Parathyroid hormone (iPTH) levels showed a broad distribution, with a median of 189.30 pg/mL, reflecting variations in secondary hyperparathyroidism among patients." (PMID 40551948, 2025).
secondary hyperparathyroidism (continued). "This hypovitaminosis D elevates parathyroid hormone (PTH) levels, leading to secondary hyperparathyroidism, which contributes to additional disorders and increases susceptibilities, particularly to non-skeletal conditions." (PMID 39940457, 2025). "A few numbers of patients also develop secondary hyperparathyroidism, which in turn leads to elevated PTH levels." (PMID 40890774, 2025). "Secondary hyperparathyroidism (SHPT) is characterized by elevated levels of parathyroid hormone (PTH), parathyroid hyperplasia, calcium and phosphorus metabolism disorders, as well as clinical conditions such as renal bone disease and vascular calcification." (PMID 40115780, 2025). "Secondary hyperparathyroidism increases the secretion of parathyroid hormone, which promotes bone resorption and releases calcium into the bloodstream, but this also results in decreased bone density." (PMID 40428054, 2025). "Over recent years, calcimimetics have garnered significant attention due to their ability to reduce serum parathyroid hormone levels in secondary hyperparathyroidism." (PMID 40135106, 2025). "Secondary hyperparathyroidism is common in patients with chronic heart failure and serum PTH levels correlated with reduced BMD in this patient population." (PMID 41515999, 2025). "Yet, in chronic kidney disease, there is a development of resistance to FGF-23 signaling, so PTH is persistently elevated, contributing to secondary hyperparathyroidism (SHPT)." (PMID 40564142, 2025). "While PTH has been a long-established biomarker for measuring and monitoring the progression of secondary hyperparathyroidism, it has also been proposed as a biomarker for CKD." (PMID 40564142, 2025). "The positive correlation between Ca × P and PTH reflects the well-established relationship between hyperphosphatemia and secondary hyperparathyroidism in CKD." (PMID 41565306, 2025). "Elevated parathyroid hormone (PTH) levels, a hallmark of secondary hyperparathyroidism in CKD, drive excessive bone resorption, weakening bone integrity." (PMID 39795624, 2025). "Tertiary hyperparathyroidism, finally, is characterized by autonomous and excessive secretion of parathyroid hormone (PTH) following prolonged secondary hyperparathyroidism, commonly observed in patients with chronic kidney disease." (PMID 40710393, 2025). "Another critical diagnostic nuance is that while parathyroid hormone (PTH) levels are usually normal at diagnosis in XLH, there are exceptions, and multiple authors have reported secondary hyperparathyroidism in XLH even before treatment." (PMID 41185884, 2025). "This unexpectedly resulted in a marked increase in PTH levels and bone formation markers, suggesting the worsening of secondary hyperparathyroidism." (PMID 41190261, 2025). "Calcimimetics are a useful option for PTH control in secondary hyperparathyroidism and parathyroid autonomy across the CKD spectrum." (PMID 41303180, 2025). "As kidney function deteriorates, the level of circulating PTH increases, leading to secondary hyperparathyroidism." (PMID 40870903, 2025). "Secondary hyperparathyroidism includes an increase in PTH expression, synthesis, and secretion and excessive proliferation of parathyroid cells, resulting in parathyroid hypertrophy." (PMID 40218942, 2025). "They identified 4 groups characterized as 'rapid PTH drop', 'gradual PTH decrease', 'slow PTH decrease with high phosphate', and 'uncontrolled secondary hyperparathyroidism'." (PMID 40131582, 2025). "PTX has emerged as a standard therapeutic intervention aimed at addressing secondary hyperparathyroidism and its associated complications, such as UTC, by reducing parathyroid hormone (PTH) levels and controlling calcium-phosphorus imbalance." (PMID 41353129, 2025). "In contrast to secondary hyperparathyroidism observed in patients with PA, primary hyperparathyroidism is characterized by autonomous secretion of PTH due to parathyroid hyperplasia or adenoma, resulting in hypercalcaemia." (PMID 40608198, 2025).
secondary hyperparathyroidism (continued). "In secondary hyperparathyroidism, PTH levels usually respond to medical management—especially with calcimimetics, resulting in reduced PTH secretion." (PMID 41301699, 2025). "In patients with both primary and secondary hyperparathyroidism undergoing treatment with calcimimetics, regular monitoring of PTH, calcium, and phosphorus levels is essential." (PMID 41210046, 2025). "The persistence of abnormal calcium and phosphate metabolism and the reduction of bone response to PTH makes this compensation ineffective and promotes the progression of secondary hyperparathyroidism (sHPT)." (PMID 38223338, 2024). "Corticosteroids can induce secondary hyperparathyroidism, characterized by elevated levels of parathyroid hormone (PTH)." (PMID 38558655, 2024). "Cimetidine was used to decrease parathyroid hormone levels in patients with secondary hyperparathyroidism." (PMID 38910668, 2024). "Despite the apparent beneficial effect exhibited by PTH signaling, the reality of both primary and secondary hyperparathyroidism is vastly different." (PMID 38785509, 2024). "Accurate diagnosis and treatment monitoring of secondary hyperparathyroidism requires measurement of PTH." (PMID 39364464, 2024). "Additionally, the classical pathogenesis of anemia in dialysis-dependent patients is usually associated with excessive PTH secretion and secondary hyperparathyroidism (HPTS) with subsequent fibrosis of bone marrow that could interfere with erythropoiesis and increase the required ESA dose." (PMID 39179496, 2024). "Reduced renal function can lead to decreased activation of vitamin D and retention of phosphorus, potentially lowering serum calcium levels and leading to increased PTH secretion, then secondary hyperparathyroidism." (PMID 38172731, 2024). "In line with previous studies, PTH correlated inversely with 25OHD, consequently 12% of patients displayed secondary hyperparathyroidism." (PMID 38523666, 2024). "Dr. Slatopolsky developed a very sensitive PTH radioimmunoassay to elucidate the pathophysiology of secondary hyperparathyroidism." (PMID 39364464, 2024). "Low levels of vitamin D therefore lead to the development of secondary hyperparathyroidism (as mentioned) with elevated PTH secretion." (PMID 39518465, 2024). "In response to low blood calcium, the parathyroid glands release PTH, resulting in an inverse relationship between the Vit D and PTH levels, clinically referred to as secondary hyperparathyroidism." (PMID 39449502, 2024). "Which depicts laboratory values since 2020, a typical pattern of secondary hyperparathyroidism was evident, characterized by declining calcium levels as the disease advances, in contrast to increasing phosphorus and parathyroid hormone levels." (PMID 39130819, 2024). "Tertiary hyperparathyroidism describes the autonomous and excessive secretion of parathyroid hormone (PTH) by the parathyroid glands after longstanding secondary hyperparathyroidism in chronic kidney disease." (PMID 38182973, 2024). "Secondary hyperparathyroidism with parathyroid hormone (PTH) levels reduced to 500 pg/ml, with complete remission of acidosis, hypophosphatemia, and hypouricemia throughout her outpatient follow-up." (PMID 38962632, 2024). "This lowering of serum calcium increases PTH secretion, which stimulates the production of calcitriol in the kidneys, so that serum calcitriol is kept at normal levels at the expense of higher serum PTH (secondary hyperparathyroidism)." (PMID 39114236, 2024). "He showed other manifestations of chronic kidney disease including hyperphosphatemia, secondary hyperparathyroidism (peak PTH 10 pmol/L), and fluctuations of the kidney function that worsened with acute illnesses and dehydration." (PMID 37576556, 2023). "Managing secondary hyperparathyroidism involves addressing mineral and bone disorders through dietary interventions, phosphate binders, and medications to regulate PTH levels." (PMID 38276262, 2023).
secondary hyperparathyroidism (continued). "She showed other manifestations of chronic kidney disease, including hyperphosphatemia, secondary hyperparathyroidism (peak PTH 14 pmol/L), and fluctuations of the kidney function that worsened with acute illnesses and dehydration." (PMID 37576556, 2023). "The patients with decompensated acidosis had higher levels of phosphate and parathyroid hormone, i.e., more advanced secondary hyperparathyroidism." (PMID 37958263, 2023). "Supplementation with 20 μg vitamin D and 1000/1200 mg calcium increases the vitamin D level, suppresses secondary hyperparathyroidism (lowering the parathyroid hormone/PTH), and improves bone and muscle strength." (PMID 36901976, 2023). "Evidence from German Conn’s Registry showed that 54% of the PA patients had secondary hyperparathyroidism; another study reported that 37% of the PA subjects presented an abnormally high PTH level; early studies also suggested a PTH elevation amid PA." (PMID 38139166, 2023). "The elevated ALP group correlated with significantly higher levels of preoperative PTH and phosphorus, lower serum calcium, and a longer hospital stay for secondary hyperparathyroidism in CKD." (PMID 37627135, 2023). "Parathyroid hormone then increases to try and stimulate more of the conversion of vitamin D into its active form (secondary hyperparathyroidism)." (PMID 37034443, 2023). "Blood tests showed elevated parathyroid hormone (PTH) and calcium levels, which led to the suspicion of secondary hyperparathyroidism." (PMID 39516955, 2023). "In CKD-MBD, renal 1,25-vitamin D synthesis decreases despite secondary hyperparathyroidism (also known as PTH resistance or hyporesponsiveness)." (PMID 36862513, 2023). "The diagnosis of normocalcemic hyperparathyroidism or secondary hyperparathyroidism are clinical conditions that depend on accurate PTH reference values." (PMID 37286864, 2023). "The decrease in serum calcium level and PTH level with cinacalcet treatment has been shown previously in cases of primary hyperparathyroidism or secondary hyperparathyroidism in dialysis patients." (PMID 37069889, 2023). "PTH values were higher in those with lower calcium levels (especially at TC <2.2 nmol/L) consistent with appropriate secondary hyperparathyroidism, and higher in those with higher calcium levels (TCa >2.5 nmol/L) consistent with primary hyperparathyroidism." (PMID 37251673, 2023). "The decline in calcitriol also triggers secondary hyperparathyroidism, wherein the parathyroid glands release more parathyroid hormone (PTH) to maintain calcium balance." (PMID 38276262, 2023). "On the other hand, secondary hyperparathyroidism can alter the levels of serum calcium and phosphorus metabolism and PTH, which are common complications observed in dialysis patients." (PMID 36964507, 2023). "One well-known physiological function of 25(OH)D is to inhibit PTH in a moderate level, so as to avoid the adverse effect of elevated PTH concentration (secondary hyperparathyroidism)." (PMID 36920734, 2023). "CKD disrupts phosphorus and calcium homeostasis, and these perturbations lead to secondary hyperparathyroidism characterized by elevated parathyroid hormone levels and parathyroid hyperplasia, which are early events in most patients." (PMID 34626363, 2022). "Patients with end-stage kidney disease (ESKD) often have secondary hyperparathyroidism (SHPT) which is characterized by elevated parathyroid hormone (PTH) in response to kidney failure." (PMID 35729513, 2022). "To further investigate the in vivo inhibitory effect of the optogenetic approach on the elevated release of PTH, we established a rat model of secondary hyperparathyroidism (SHPT)." (PMID 35140213, 2022). "Glucocorticoid excess is known to cause secondary hyperparathyroidism, as patients with ACS had elevated levels of urinary calcium excretion and serum intact-PTH in this study." (PMID 36035657, 2022).
secondary hyperparathyroidism (continued). "In clinical practice, active vitamin D or an analogue is often prescribed to suppress parathyroid hormone in patients with secondary hyperparathyroidism." (PMID 34626363, 2022). "In secondary hyperparathyroidism, 25(OH)D has a synergistic effect with 1,25(OH)2D on PTH production." (PMID 36012412, 2022). "A negative correlation was described between 25-OH vitamin D and PTH levels in women after MS, which suggests that vitamin D supplementation partly improves secondary hyperparathyroidism." (PMID 35565899, 2022). "Low levels of activated 1,25(OH)2D promote the progression of secondary hyperparathyroidism via multiple pathways, including decreased intestinal absorption of calcium that further stimulates parathyroid hormone secretion." (PMID 34626363, 2022). "Cinacalet, introduced to the market in 2004, is a positive allosteric modulator of CaS calcium-sensing receptor, which is used to treat secondary hyperparathyroidism (elevated parathyroid hormone levels) as it blocks the secretion of parathyroid hormone." (PMID 36615372, 2022). "Studies in patients with CKD suggest that higher 25(OH)D levels are required to suppress parathyroid hormone levels and effectively treat secondary hyperparathyroidism." (PMID 34626363, 2022). "Serum calcium (Ca) levels are strictly regulated by parathyroid hormone and vitamin D. The imbalance of calcium ion in the patient’s body leads to secondary hyperparathyroidism, which in turn leads to the occurrence of coronary atherosclerosis." (PMID 35057500, 2022). "PTH elevation was seen in 67 women, and among them, 31 subjects had vitamin D level 30–50 nmol/L and 24 had levels between 50–75 nmol/L, consistent with secondary hyperparathyroidism." (PMID 35684109, 2022). "The levels of FGF23 and PTH increase progressively and subsequently drive secondary hyperparathyroidism and CKD-MBD." (PMID 35622784, 2022). "The dosage of evocalcet required to control serum parathyroid hormone (PTH) levels varies among secondary hyperparathyroidism (SHPT) patients." (PMID 36512619, 2022). "The 25OH D deficiency can to lead some deleterious complications, mainly hypersecretion of parathyroid hormone (PTH) and secondary hyperparathyroidism (SHPT)." (PMID 35930297, 2022). "Parathyroid hormone (PTH) plays a role in maintaining calcium and phosphorus homeostasis, and in secondary hyperparathyroidism excess PTH secretion contributes to bone loss." (PMID 35140213, 2022). "This way, secondary hyperparathyroidism can be simulated, and the simulations predict adequate long-term changes in PTH levels." (PMID 37674998, 2022). "Our study thus provides a strategy to regulate the parathyroid and restore human PTH release in secondary hyperparathyroidism through an optogenetic approach." (PMID 35140213, 2022). "Secondary hyperparathyroidism (SHPT) is a condition in which the parathormone (PTH) level is elevated to compensate for the calcium–phosphorus imbalance." (PMID 36672533, 2022). "This blunted response to extracellular calcium by parathyroid cells isolated from patients with secondary hyperparathyroidism was consistently supported by our PTH assay, calcium fluorescence data and electrophysiological recordings." (PMID 35140213, 2022). "At the beginning of the study, serum PTH levels were markedly elevated, possibly due to a secondary hyperparathyroidism due to the length of time on conventional therapy." (PMID 35899095, 2022). "This phenomenon contributes to the development of high PTH levels and the worsening of secondary hyperparathyroidism." (PMID 36012412, 2022). "Secondary hyperparathyroidism (SHPT) is characterized by a compensatory increase in parathyroid hormone (PTH) secretion in response to decreased renal phosphate excretion, resulting in potentiating bone resorption and decreased bone quantity and quality." (PMID 36015101, 2022).